EBF2 (EBF transcription factor 2)
Description:
Transcription factor that, in osteoblasts, activates the decoy receptor for RANKL, TNFRSF11B, which in turn regulates osteoclast differentiation. Acts in synergy with the Wnt-responsive LEF1/CTNNB1 pathway. Recognizes variations of the palindromic sequence 5'-ATTCCCNNGGGAATT-3' (By similarity).
Synonyms: EBF-2; COE2; FLJ11500; O/E-3; OE-3
Tractability: PROTAC: ubiquitination databases record sites on it.
Gene: Protein-coding gene on chromosome 8 (25,841,725 to 26,045,413, reverse strand). Ensembl gene ENSG00000221818.
Subcellular location: Nucleus
Subcellular location (Human Protein Atlas): Nucleoplasm; Nuclear bodies
Pathways (Reactome):
Developmental Biology: Transcriptional regulation of brown and beige adipocyte differentiation by EBF2
Gene Ontology:
Molecular function: protein binding; DNA-binding transcription factor activity, RNA polymerase II-specific; RNA polymerase II cis-regulatory region sequence-specific DNA binding; chromatin binding; DNA binding; DNA-binding transcription activator activity, RNA polymerase II-specific; DNA-binding transcription factor activity
Biological process: positive regulation of cold-induced thermogenesis; regulation of transcription by RNA polymerase II; positive regulation of transcription by RNA polymerase II; regulation of DNA-templated transcription
Cellular component: chromatin; nucleus
Genetic constraint (gnomAD): Loss-of-function variants: 17 observed, 64.74 expected, observed/expected ratio (o/e) 0.26, 90% interval 0.18 to 0.39. The upper end of that interval is the gene's LOEUF score, 0.39, which puts it in group 1 of 6, group 1 being the genes least tolerant of losing a copy. Missense variants: 574 observed, 676.93 expected, observed/expected ratio (o/e) 0.85, 90% interval 0.79 to 0.91. Synonymous variants: 264 observed, 252.15 expected, observed/expected ratio (o/e) 1.05, 90% interval 0.95 to 1.16.
Homologues: Orthologues: chimpanzee EBF2 (99% identical), macaque EBF2 (99% identical), pig EBF2 (99% identical), dog EBF2 (99% identical), mouse Ebf2 (99% identical), guinea pig EBF2 (99% identical), rat Ebf2 (98% identical), rabbit EBF2 (98% identical), tropical clawed frog ebf2 (92% identical), zebrafish ebf2 (81% identical), Drosophila melanogaster kn (58% identical), Caenorhabditis elegans unc-3 (47% identical). Paralogues in human: EBF3 (82% identical), EBF1 (79% identical), EBF4 (72% identical).
Diseases named in the same sentence as EBF2 in open-access papers:
EBF2 is named in the same sentence as 31 diseases in open-access papers, as found by Europe PMC text mining. Sharing a sentence is not in itself a finding about the gene and the disease. The quoted sentences say what the papers report.
Obesity (6 papers, 2018 to 2023). Accumulation of substantial excess body fat. "Transgenic mice overexpressing the transcription factor EBF2 were protected from HFD-induced obesity since EBF2 robustly stimulated beige adipocyte development in the WAT of mice, even under conditions of thermoneutrality." (PMID 29478099, 2018).
osteosarcoma (5 papers, 2019 to 2023). A usually aggressive malignant bone-forming mesenchymal neoplasm, predominantly affecting adolescents and young adults. "Meanwhile, has-miR-182-3p participates in the pathogenesis of pulmonary arterial hypertension vascular remodeling as well as in the regulation of osteosarcoma through the EBF2 regulation pathway." (PMID 37566020, 2023). "EBF2 is an E3 ubiquitin-protein ligase that can promote osteosarcoma occurrence and development." (PMID 36611207, 2023). "In osteosarcoma, miR204 has been indicated to suppress the cell viability via targeting EBF2." (PMID 31333725, 2019).
Inguinal hernia (4 papers, 2015 to 2023). Protrusion of the contents of the abdominal cavity through the inguinal canal. "Jorgenson and colleagues previously identified 4 inguinal hernia susceptibility loci purported to result in reduced MMP activity: WT1, EFEMP1, EBF2 and ADAMTS6." (PMID 36584111, 2022). "We identified four novel inguinal hernia genetic susceptibility loci near the genes WT1, EFEMP1, EBF2 and ADAMTS6, and confirmed those associations in an independent cohort." (PMID 26686553, 2015). "These loci for inguinal hernia susceptibility are EFEMP1, WT1, EBF2, and ADAMTS6." (PMID 31024927, 2019).
breast carcinoma (3 papers, 2009 to 2022). "Although little is known about the role of EBF2 in breast cancer development, studies have shown that inactivation of EBF genes can lead to tumorigenesis via accumulation and expansion of undifferentiated progenitor cells." (PMID 36344993, 2022). "Four additional V loci were identified from looking up MD and breast cancer susceptibility SNPs in GWAS of V, including 5q23.2 (PRDM6), 8p21.2 (EBF2), 12p12.1 (SSPN), and 16q12.2 (FTO)." (PMID 36344993, 2022). "Four additional loci for MD or breast cancer risk, 5q23.2 (PRDM6), 8p21.2 (EBF2), 12p12.1 (SSPN), and 16q12.2 (FTO), were also found associated with V." (PMID 36344993, 2022).
chronic myeloid leukemia (2 papers, 2010 to 2021). "In chronic myeloid leukemia (CML) two of the genes, (TFAP2A and EBF2), demonstrated increased methylation in blast crisis compared to chronic phase (P < 0.05)." (PMID 20184741, 2010).
glioma (2 papers, 2021 to 2022). A benign or malignant brain and spinal cord tumor that arises from glial cells (astrocytes, oligodendrocytes, ependymal cells). "Yet, three of them, FABP3, RGS16, and EBF2, are relevant for glioma biology." (PMID 35563134, 2022). "Interestingly, FABP3 and RGS16 have been proposed as markers of invasive glioma, and EBF2 positively regulates neuronal migration." (PMID 35563134, 2022).
prostate carcinoma (2 papers, 2015 to 2017). A carcinoma that arises from epithelial cells of the prostate gland. "Moreover, 8 of these TFs (FOXJ2, GATA6, NFE2L1, NFIL3, PRRX2, TEF, EBF2 and ZBTB18) were found to be differentially expressed in this study making them not only candidate biomarkers of prostate cancer but also potential therapeutic targets." (PMID 28380430, 2017).
acute lymphoblastic leukemia (1 paper, 2015). Leukemia with an acute onset, characterized by the presence of lymphoblasts in the bone marrow and the peripheral blood. "Transcription factor AP-2 alpha (TFAP2A) and Early B-Cell Factor 2 (EBF2) were identified as epigenetic molecular markers in Acute lymphoblastic leukemia (ALL) and CML-BP." (PMID 25575817, 2015).
breast tumors (1 paper, 2010). "Our preliminary data for transcription factor EBF2 suggests that this indeed is the case (EBF2 is methylated in >25% of lung and breast tumors, data not shown)." (PMID 20184741, 2010).
dwarfism (1 paper, 2022). "Global Ebf2 deletion, in turn, has previously been shown to result in dwarfism and impaired viability in mice." (PMID 35137272, 2022).
endometrial cancer (1 paper, 2023). Primary or metastatic malignant neoplasm involving the endometrium (mucous membrane that lines the endometrial cavity). "In this study, we found EBF2 to be a risk gene for endometrial cancer, and its expression levels in tumor tissues were lower than those in normal tissues." (PMID 36611207, 2023).
male infertility (1 paper, 2023). The inability of the male to effect fertilization of an ovum after a specified period of unprotected intercourse. "In this study, we plan to address: (a) the role of MKRN2 in male infertility; (b) whether MKRN2 regulates the expression level of STAT1; and (c) how MKRN2 induces the expression levels of SIX4 and TNC by the transcription factor EBF transcription factor 2 (EBF2)." (PMID 36967804, 2023).
myeloma (1 paper, 2021). "Specifically, we found that healthy MSCs exposed to MM cells underwent gains (HOXA9, ACVR2A, EBF2) and losses (HOXA2, HOXA3, HOXC5) of DNA methylation in the direction of those observed for MSCs from myeloma patients." (PMID 33462210, 2021).
Pancreatic Cancer (1 paper, 2024). "Seven genes were identified in mass spectrometry and bioinformatic analysis, all significantly downregulated in pancreatic cancer (GEO data, GSE32676), including TSPYL2, TSR1, METAP2, CYR61, EBF2, CIRBP, and TGFBR3." (PMID 38015024, 2024).
pancreatic ductal adenocarcinoma (1 paper, 2024). An infiltrating adenocarcinoma that arises from the epithelial cells of the pancreas. "Combining analyses of RNA‐seq and ChIP‐seq data, the authors further identify killin (KLLN) as a transcriptional target of KMT2D and EBF2 in pancreatic ductal adenocarcinoma (PDAC) cells." (PMID 38015024, 2024).
tumor (8 papers, 2009 to 2025). "Further, hsa-miR-532-3p along with hsa-miR-139 are associated with CHRD, FLAD1, MT1JP, and EBF2 in our analysis and have been identified as tumor suppressors in HCC that inhibit cell proliferation, migration, and invasion." (PMID 32228601, 2020). "The expression level of EBF2 was negatively correlated with tumor stage, lymph node metastasis, and distal metastasis in PDAC patients." (PMID 38015024, 2024). "The TMA was subjected to IHC staining, showing that EBF2 was mainly located in the nuclei of both normal and PDAC tumor cells." (PMID 38015024, 2024). "As for tumor grade, we combined Grades 1 and 2 and observed that the expression of EBF1, EBF2, and EBF4 increased in Grade 3 tumors, in comparison with Grades 1 and 2 (all P<0.001)." (PMID 34100918, 2021). "Rescue experiments were also performed to testify whether the tumor suppressive effect of KMT2D and EBF2 is mediated by KLLN." (PMID 38015024, 2024).
cancer (6 papers, 2019 to 2025). A tumor composed of atypical neoplastic, often pleomorphic cells that invade other tissues. "EBF2 has been found to be associated with prostate, bone, hematological and epithelial cancers." (PMID 31146393, 2019).
infection (1 paper, 2016). The state of being infected such as from the introduction of a foreign agent such as serum, vaccine, antigenic substance or organism. "In this study, transcription profiles of EIN3 during the pathogen infection was elevated in GmCYP82A3 overexpression plants, whereas, EBF2 showed suppression effect." (PMID 27588421, 2016). "EBF2 (Ein3-binding F box protein 2) which regulate EIN3 protein degradation, the expression was suppressed both before and after infection compared with WT and EV." (PMID 27588421, 2016).
peripheral neuropathy (1 paper, 2022). A disorder affecting the peripheral nervous system. "All of these TFs have previously been linked to neurogenesis or neuronal differentiation; most interestingly, the top two identified TFs, PAX6 and EBF2, have been shown to be associated with peripheral neuropathy." (PMID 35884461, 2022).
EBF2 also shares sentences with these, for which no sentence is quoted: autism spectrum disorder (1 paper); bladder cancer (1); diabetic kidney disease (1); fibrosis (1); Hepatic steatosis (1); Hernia (1); Intellectual disability (1); migraine (1); mucocutaneous lymph node syndrome (1); partial lipodystrophy (1); psychiatric disorder (1); pulmonary arterial hypertension (1).